PLLP (plasmolipin)
Description:
Main component of the myelin sheath that plays an important role in myelin membrane biogenesis and myelination. Plays an essential function in apical endocytosis. Regulates epithelial development through the regulation of apical endocytosis (By similarity). Part of the intracellular machinery that mediates basolateral-to-apical transport of ICAM-1, an essential adhesion receptor in epithelial cells, from the subapical compartment in hepatic epithelial cells.
Synonyms: PMLP; TM4SF11
Tractability: Antibody: UniProt places it where antibodies can reach, with high confidence; its Gene Ontology location is reachable by antibodies, with high confidence; UniProt predicts a signal peptide or a membrane-spanning region. PROTAC: ubiquitination databases record sites on it.
Gene: Protein-coding gene on chromosome 16 (57,248,547 to 57,284,675, reverse strand). Ensembl gene ENSG00000102934.
Subcellular location: Cell membrane; Myelin membrane; Apical cell membrane; Golgi apparatus
Gene Ontology:
Molecular function: identical protein binding; protein binding; structural constituent of myelin sheath
Biological process: myelin assembly; regulation of transcytosis; myelination; regulation of endocytosis; monoatomic ion transport
Cellular component: Golgi apparatus; myelin sheath; plasma membrane; apical plasma membrane; membrane; compact myelin; membrane raft
Genetic constraint (gnomAD): Loss-of-function variants: 14 observed, 15.63 expected, observed/expected ratio (o/e) 0.9, 90% interval 0.59 to 1.4. The upper end of that interval is the gene's LOEUF score, 1.4, which puts it in group 5 of 6, group 1 being the genes least tolerant of losing a copy. Missense variants: 241 observed, 222.89 expected, observed/expected ratio (o/e) 1.08, 90% interval 0.97 to 1.2. Synonymous variants: 105 observed, 98.75 expected, observed/expected ratio (o/e) 1.06, 90% interval 0.91 to 1.25.
Homologues: Orthologues: chimpanzee PLLP (99% identical), pig PLLP (91% identical), mouse Pllp (90% identical), guinea pig PLLP (86% identical), dog PLLP (75% identical), rabbit PLLP (75% identical), rat Pllp (73% identical), macaque PLLP (67% identical), tropical clawed frog pllp (53% identical), zebrafish pllp (43% identical), Caenorhabditis elegans F28H1.4 (25% identical), Caenorhabditis elegans F47B3.3 (20% identical). Paralogues in human: CMTM8 (39% identical), CMTM4 (24% identical), MALL (23% identical), MAL (23% identical), MARVELD1 (21% identical), MAL2 (20% identical), CMTM7 (18% identical), PLP2 (16% identical), CMTM5 (15% identical), CMTM1 (14% identical), CMTM3 (14% identical), CMTM6 (12% identical), and 2 more.
Diseases named in the same sentence as PLLP in open-access papers:
PLLP is named in the same sentence as 22 diseases in open-access papers, as found by Europe PMC text mining. Sharing a sentence is not in itself a finding about the gene and the disease. The quoted sentences say what the papers report.
breast carcinoma (3 papers, 2017 to 2024). "Using xenografts in nude mouse models of human breast cancer and melanoma metastasis, PLLP was found specifically upregulated in tumor cells that metastasize to the brain." (PMID 37345137, 2023). "Using human breast cancer and melanoma cell lines inoculated in nude mice, it was found that PLLP upregulates in cancer cells metastasized to the brain, raising the possibility that PLLP is involved in the colonization of the brain by these types of cancers." (PMID 37345137, 2023). "Previous studies have found a significant increase in PLLP expression in mouse models of breast cancer and melanoma brain metastasis, and speculated that it may play a role in brain metastasis of these two malignant tumors." (PMID 39872525, 2024). "However, we have now shown that the expressions of SLC8A2 and PLLP were upregulated in metastasizing breast cancer and melanoma cells in the brain." (PMID 28210624, 2017).
schizophrenia (2 papers, 2012 to 2021). A major psychotic disorder characterized by abnormalities in the perception or expression of reality. "PLLP is presumably involved in various disorders, such as cancer, schizophrenia, Alzheimer’s disease, and type 2 diabetes mellitus." (PMID 34955555, 2021).
Alzheimer disease (1 paper, 2021). A progressive, neurodegenerative disease characterized by loss of function and death of nerve cells in several areas of the brain leading to loss of cognitive function such as memory and language. "A higher PLLP content was revealed in neocortical samples from Alzheimer’s patients by a proteomics analysis, implicating PLLP in Alzheimer’s disease." (PMID 34955555, 2021).
Cerebral ischemia (1 paper, 2025). Restriction of arterial blood supply to the brain associated with insufficient oxygenation to support the metabolic requirements of the tissue. "Consistent with this, we also observed a significant downregulation of PLLP expression in both cerebral ischemia and hindlimb ischemia mouse models." (PMID 40379643, 2025).
cyst (1 paper, 2021). A sac-like closed membranous structure that may be empty or contain fluid or amorphous material. "It is important to note that a stx7, EpsR, or PLLP knockdown in MDCK cells distorts the cyst formation in a 3D culture and alters the Rab11 distribution, indicating that PLLP is involved in the function of the SNARE proteins." (PMID 34955555, 2021).
endometrial carcinoma of the (1 paper, 2024). "Recent study have reported a significant correlation between PLLP and renal smoky cell carcinoma, renal clear cell carcinoma, and endometrial carcinoma of the uterine corpus." (PMID 39872525, 2024).
hyperalphalipoproteinemia (1 paper, 2021). An autosomal dominant genetic condition caused by mutation(s) in the CETP gene, encoding cholesteryl ester transfer protein. "It should be noted that three nsSNPs were found in PLLP, implicating PLLP in lipid metabolism and hyperalphalipoproteinemia." (PMID 34955555, 2021).
keratoconus (1 paper, 2018). A degenerative, structural disorder of the eye, characterized by a cone-shaped protrusion of the cornea. "We also identified plasmolipin and Notch1 as being significantly reduced in keratoconus for both gene and protein expression (p < 0.05)." (PMID 29321650, 2018).
Parkinson disease (1 paper, 2020). A progressive degenerative disorder of the central nervous system characterized by loss of dopamine producing neurons in the substantia nigra and the presence of Lewy bodies in the substantia nigra and locus coeruleus. "The genes that directly interact with PLLP are involved in cell-to-cell communication and neurological-related diseases, such as the completion and maintenance of myelin sheath (MOG), the ion transporter (SLC31A2) (Schweigel-Röntgen, 2014), and Parkinson’s disease (DBNDD2)." (PMID 33304381, 2020).
small cell lung carcinoma (1 paper, 2024). Small cell lung cancer (SCLC) is a highly aggressive malignant neoplasm, accounting for 10-15% of lung cancer cases, characterized byrapid growth, and early metastasis. "In this study, we found that the expression of PLLP is down-regulated in small cell lung cancer and the results of enrichment analysis indicated its involvement in biological functions such as compact myelin, myelin sheath, and structural constituent of myelin sheath." (PMID 39872525, 2024).
type 2 diabetes mellitus (1 paper, 2021). A type of diabetes mellitus that is characterized by insulin resistance or desensitization and increased blood glucose levels. "The PLLP and Stx7 expression levels in skin samples from patients with type 2 diabetes mellitus is far lower than in healthy people." (PMID 34955555, 2021). "PLLP is possibly involved in complications of type 2 (insulin-independent) diabetes mellitus." (PMID 34955555, 2021).
cancer (10 papers, 2014 to 2026). A tumor composed of atypical neoplastic, often pleomorphic cells that invade other tissues. "Below we will compare mechanisms active during pLLP migration to other examples of collective cell migration and then focus on how collectively invading cancer cells subvert these mechanisms to invade surrounding tissues." (PMID 30175096, 2018). "Although the Src pathway is certainly already a heavily studied one in cancer research, it provided an excellent opportunity to demonstrate that zebrafish PLLp migration can be used to effectively identify anti-metastatic compounds that work in vivo." (PMID 25810455, 2015). "We showed that the Src inhibitor SU6656 significantly reduced tumor metastasis in mice, demonstrating that similar mechanisms are used to control both cell migration during PLLp migration in zebrafish and cancer metastasis." (PMID 25810455, 2015). "Understanding how these signaling pathways regulate collective cell migration of the pLLP may provide clues as to how these pathways are hijacked during cancer invasion." (PMID 30175096, 2018). "MAL (LUAD, THYM, and UCEC), MAL2 (BRCA, PAAD, and UCEC), and PLLP (KICH, KIRC, and UCEC) present strong correlations (p ≤ 0.001) in three types of cancer, and MALL (KIRC and PAAD), CMTM8 (KIRC and KIRP), and MYADM (LUSC and THYM) do so in two cancer types." (PMID 37345137, 2023). "PLLP has been found to be up-regulated in brain tissues harboring metastases; however, the clinical significance of PLLP in cancer has not yet been clarified." (PMID 37958393, 2023). "Tetraspanins, of which mRNA for TM4SF4, TM4SF20 and PLLP were increased >10-fold in SSA/Ps, regulate cell adhesion and proliferation by binding integrins and growth factor receptors, are increased in multiple types of cancer and regulate epithelial-to-mesenchymal transition." (PMID 24533081, 2014). "No information was available on the role of PLLP and FAM321A in cancer." (PMID 32911675, 2020).
tumor (7 papers, 2015 to 2026). "Specifically, PLLP was highly expressed in endothelial cells at the periphery of the tumor, where oxygen concentration is high, but exhibited significantly lower expression in endothelial cells within the hypoxic core of the tumor." (PMID 40379643, 2025). "The antitumor effect of PLLP in vivo was verified by tumor formation experiments in nude mice." (PMID 41791705, 2026). "Supporting these observations, our findings also demonstrated that overexpressing PLLP markedly reduced the survival and angiogenic capacities of HUVECs under hypoxia, further indicating a protective role of PLLP against tumor cell transformation in a hypoxic microenvironment." (PMID 40379643, 2025). "In conclusion, we have shown that PLLp migration can be used as an effective model to rapidly identify potent compounds that comprise anti-metastatic activity, and the effectiveness of these compounds can be demonstrated in mammalian tumor models." (PMID 25810455, 2015). "This is especially evident in the cases of MALL, PLLP, and MYADM, whose function in normal and tumor cells needs further investigation using established cell model systems, and that in the case of MYADML2, which is yet to be examined." (PMID 37345137, 2023). "To demonstrate that inhibiting migration of the zebrafish PLLp can be used to identify anti-metastatic compounds we selected the Src inhibitor SU6656, which has a published effective pharmacologic dose in mice, for follow-up studies in a mouse tumor model." (PMID 25810455, 2015).
infection (1 paper, 2019). The state of being infected such as from the introduction of a foreign agent such as serum, vaccine, antigenic substance or organism. "In P. monodon, two isoforms of plasmolipin, Pm PLP1 and Pmp LP2, was upregulated in haemocytes after infection with yellow head virus (YHV) and WSSV (Vatanavicharn, Pongsomboon & Tassanakajon, 2012)." (PMID 31875142, 2019).
PLLP also shares sentences with these, for which no sentence is quoted: melanoma (3 papers); gastric cancer (1); glioblastoma (1); meningioma (1); pancreatic cancer (1); pituitary adenomas (1); renal clear cell carcinoma (1); Virus Infection (1).